ACE (angiotensin I converting enzyme)
Diseases named in the same sentence as ACE in open-access papers (continued):
Sharing a sentence is not in itself a finding about the gene and the disease.
Hypertension (continued). "However, in addition to their role in controlling blood pressure, ACE inhibitors have been shown to be effective in preventing cognitive decline and improving cognitive function in patients with hypertension." (PMID 26300914, 2015). "These interaction models and epistasis networks amongst AGT, ACE, and AT1R genes may be regarded as potential biomarkers for hypertension susceptibility." (PMID 25961019, 2015). "This research investigated and revealed that Soursop fruit extracts possess antioxidant properties and were able to inhibit key enzymes relevant to type-2 diabetes mellitus (α-amylase and α-glucosidase) and hypertension (angiotensin-I converting enzyme) in vitro." (PMID 26788368, 2015). "The association between these polymorphisms and the ACE gene is similarly discrepant between its association with hypertension in the Japanese and its nonassociation in the Chinese." (PMID 26491214, 2015). "Synthetic ACE inhibitors (captopril, enalapril, lisinopril, etc.), renin inhibitor (aliskiren), and angiotensin receptor blockers are traditionally used to treat congestive heart failure and hypertension." (PMID 26715103, 2015). "Angiotensin-converting enzyme (ACE) and Ang II are involved in the remodeling of large and resistance arteries during hypertension, and inflammatory and tissue responses, and matrix remodeling are regulated by signaling events downstream of the Ang II type 1 receptor (AT1)." (PMID 26006249, 2015). "The special attention given to the RAS gene polymorphisms is not only due to the fact that its components play an important role in regulation of vascular homeostasis, but also because of the place of angiotensin I converting enzyme (ACE) inhibitors in the therapeutic management of the hypertension." (PMID 26351579, 2015). "Indeed, treatment with statins, ACE inhibitors, beta blockers and calcium channel blockers was more frequent in patients with hypertension (all p≤0.003)." (PMID 26237513, 2015). "Thus, the aim of this study was to evaluate the relation between the RAS genes polymorphisms (AGT 235M/T, ACE I/D, and AT1R 1166A/C) and the essential hypertension in the population of Burkina Faso and to determine hypertension main risk factors." (PMID 26351579, 2015). "Based on these observations, ACE inhibition was considered a pivotal target for treatment of hypertension, and together with a model of somatic ACE (sACE), a metallopeptidase with a zinc-binding carboxyl group at the catalytic center, led to design of captopril." (PMID 26661890, 2015). "Differences in treatment of hypertension including use of ACE inhibitors which could probably account for this variation need to be evaluated in further studies." (PMID 26238594, 2015). "The logistic regression analysis confirmed that the DD genotype of the ACE gene is a risk factor that would increase by nearly 4 times the incidence of hypertension among patients, regardless of other environmental risk factors." (PMID 26351579, 2015). "Furthermore, studies have demonstrated that modulation of ACE from the lungs have important implications in the development of hypertension." (PMID 25971747, 2015). "The genetic variation of ACE contributes to the balance of fibrinolytic pathway, which may be one of the pathological mechanisms linking the ACE genotype and essential hypertension." (PMID 25973747, 2015). "Consistently, previous studies have shown that ACE inhibitors could decrease Hcy levels in essential hypertension." (PMID 26640794, 2015). "Since the discovery of ACE inhibitors in snake venom, many synthetic inhibitors have been developed and are currently used in the treatment of essential hypertension and heart failure in humans; these inhibitors include captopril, enalapril, alacepril and lisinopril." (PMID 26691527, 2015).
Hypertension (continued). "In the HCHF diet-induced high blood pressure and vascular dysfunction reported here, the antioxidant, anti-inflammation and ACE inhibition of FA could account for the antihypertensive and vascular protective effects." (PMID 26247970, 2015). "Zofenopril calcium, a prodrug of the active compound zofenoprilat, is an ACE-inhibitor which has been successfully and safely employed in the treatment of essential hypertension and acute myocardial infarction or heart failure, also in subgroups of patients with high BP." (PMID 26347187, 2015). "Besides oxidative stress-induced hypertension, a widely accepted signaling pathway of hypertension is through the angiotensin-I-converting enzyme (ACE), which plays an important role in the regulation of blood pressure." (PMID 24672576, 2014). "However, several factors affect HRV; cigarette smoking has been linked to low HRV, beta-blockers and ACE-inhibitors increase HRV and, diabetes mellitus and hypertension has been shown to decrease HRV." (PMID 24695370, 2014). "Our study demonstrates that hypertension, but not the ACE I/D polymorphism, is associated with a risk of small-vessel stroke in south Indian population." (PMID 24523965, 2014). "This vasoregulatory role has been exploited clinically through the introduction of inhibitors to the angiotensin-II generating/bradykinin-degrading protease, angiotensin-converting enzyme (ACE), that still represent the front-line therapeutics for the treatment of hypertension." (PMID 25161395, 2014). "This hypothesis can be tested by studying ACE2 levels in various cardiovascular diseases as was proven in an accompanying paper, such as hypertension and heart failure, where ACE inhibitors are particularly effective." (PMID 24691203, 2014). "We also show that medications used to treat, for example, hypertension such as dihydropyridine derivatives, but not ACE-inhibitors or selective β-blockers agents, cause or maintain an increase in the inflammatory response cascade via high IL-6 levels." (PMID 25147954, 2014). "Evidence for a pathogenic role of renal ACE is the demonstration that genetic deletion of renal ACE expression prevented hypertension produced by subcutaneous administration of Ang II, suggesting a specific renal ACE-dependent mechanism of hypertension in this model." (PMID 25071727, 2014). "From 2009–2010, the most commonly prescribed hypertension treatments in Russia were angiotensin-converting enzyme (ACE) inhibitors (63% of patients), diuretics (37%), beta blockers (31%), calcium channel blockers (CCBs; 15%), and angiotensin receptor blockers (ARBs; 5%)." (PMID 25141122, 2014). "Accordingly, ACE inhibitors are routinely prescribed to patients with hypertension." (PMID 25222748, 2014). "However, diabetics were also more frequently treated with drugs that recognizably increase circulating EPCs numbers, such as ACE-inhibitors and ARBs, what would counterbalance the possible reduction on EPCs numbers due to the higher prevalence of hypertension." (PMID 24934236, 2014). "ACE inhibitors have become the drug of choice for treating obesity-related hypertension in adults." (PMID 24522942, 2014). "About antihypertensive property, it is well known that, in recent years, the treatment of hypertension has achieved a breakthrough with the identification of ACE inhibitors as a modern therapeutic tool and considerable interest has focused on the action of ACE inhibitors." (PMID 24616741, 2014). "Thus, RAAS pathway blockade by inhibiting ACE activity is one goal in treating the hypertension characteristic of metabolic syndrome and obesity." (PMID 25280587, 2014). "In view of the fact that hormonal changes during pregnancy can be related to central imbalances that can lead to hypertension, we measured ACE and ACE2 activity, components of the renin-angiotensin system (RAS) in the total tissue extracts from the hypothalami of the studied groups." (PMID 25405471, 2014).
Hypertension (continued). "CKD-related complications such as proteinuria or hypertension could then be treated with a renin-angiotensin-aldosterone antagonist such as an ACE-inhibitor or an angiotensin receptor blocker." (PMID 25416588, 2014). "Angiotensin-Converting Enzyme inhibitors (ACE-i) were originally developed to target hypertension but now have additional clinical indications such as congestive heart failure, left ventricular dysfunction, atherosclerotic vascular disease and diabetic nephropathy." (PMID 25632296, 2014). "The use of angiotensin-converting enzyme (ACE) inhibitors or angiotensin II receptor blockers (ARBs), could reduce both CV morbidity and mortality across populations that apart from hypertension, had other co-morbid conditions." (PMID 25344747, 2014). "In addition, cocoa seed extract inhibition of ACE also explains the likely mechanism for its use in the treatment of hypertension." (PMID 25295218, 2014). "Protein hydrolysate or peptides with both ACE inhibitory and antioxidant activities might be helpful in treating hypertension." (PMID 25185066, 2014). "Hence the design of novel, second generation ACE inhibitors that selectively target C‐ACE for the treatment of hypertension and cardiovascular diseases remains a clinically important goal." (PMID 24289879, 2014). "This cross-sectional study from a single health facility in Africa may give clues to the effect of ACE inhibitors in the treatment of hypertension and their effect on LVH in black patients." (PMID 24444396, 2014). "As therapeutic strategies that block the RAS using ACE inhibitors or Ang II receptor blockers are first line therapy in hypertension, experimental studies are needed that combine ACE2 activators/recombinant ACE2 with RAS blockers to determine if this approach offers incremental benefits." (PMID 25009501, 2014). "Furthermore, ACE inhibitors have been shown to exert beneficial effects on cardiovascular disease and reduce mortality as a result of hypertension." (PMID 24959250, 2014). "A recent work from Navar’s group and our collaborator Casarini’s group revealed that the maintenance of high blood pressure in 2K1C is dependent of an imbalance between high levels of ACE/Ang II and low levels of ACE2/Ang 1–7, both being influenced by renin activity." (PMID 25223948, 2014). "However, these synthetic drugs have been described to have some side effects and, thus, natural sources of ACE inhibitors are being investigated as a milder but effective alternative for the control of high blood pressure." (PMID 24619242, 2014). "Likewise, spontaneously hypertensive rats (SHRs), an animal model of human essential hypertension, functionally express ACE on endothelial cells and SMCs." (PMID 25222748, 2014). "ACE inhibitors block the formation of Ang II and have been used to treat hypertension." (PMID 24475296, 2014). "Moreover, this hypomethylation occurs simultaneously with an increase in the ACE protein activity and high blood pressure levels in these children." (PMID 25170764, 2014). "The percentage of use of ACE inhibitors or ARBs in aware diabetic persons with known hypertension in our study was relatively low (58.8%) considering that, according to recommendations all such persons should receive hypertensive treatment with one drug from this group." (PMID 23637851, 2013). "Angiotensin converting enzyme (ACE) inhibitors plays a critical role in treating hypertension." (PMID 24359711, 2013). "Overactivation of brain Angiotensin-converting enzyme (ACE) - Angiotensin II (Ang II) - Angiotensin II type 1 receptor (AT1R) axis was found to be involved in the progress of hypertension, atherosclerosis and thrombogenesis, which increased the susceptibility to ischemic stroke." (PMID 23997755, 2013). "As expected, ACE inhibition prevented hypertension development throughout the experiment." (PMID 24244677, 2013).
Hypertension (continued). "ACE inhibitory fractions from Jatropha kernel have potential applications in alternative hypertension therapies, adding a new application for the Jatropha plant protein fraction and improving the financial viability and sustainability of a Jatropha-based biodiesel industry." (PMID 24224169, 2013). "ACE I/D polymorphism and ACE activity revealed significant influence on hypertension, while circulating ACE mRNA expression was not important factors associated with hypertension in this Chinese population." (PMID 24098401, 2013). "Therefore, the inhibition of ACE has been viewed as a therapeutic target for the treatment of hypertension." (PMID 24093919, 2013). "are utilized for the treatment of hypertension in traditional medicine and this research revealed that the mechanism of action of the three mentioned plants in treatment of hypertension could be done through ACE inhibition." (PMID 24359711, 2013). "Similarly, inhibition of angiotensin-1 converting enzyme (ACE) activity is a therapeutic approach to the management of hypertension as ACE converts angiotensin-I to angiotensin-II, which is a potent vasoconstrictor which leads to elevated blood pressure." (PMID 24348547, 2013). "An 83-year-old gentleman, with chronic renal insufficiency, coronary artery disease and PAD, resistant hypertension, and intolerance to angiotensin converting enzyme (ACE) inhibitors, was diagnosed with severe left renal artery stenosis by magnetic resonance angiography (MRA)." (PMID 23819096, 2013). "Therefore, ACE has become the major target of medicine in the clinical treatment of hypertension, and some ACE-inhibitors were developed, such as captopril, enalapril, lisinopril, tenormin, and temocapril." (PMID 23638059, 2013). "Therefore, compounds with ACE inhibitory activities can be used in treating or preventing hypertension." (PMID 23666006, 2013). "ACE gene deletion is a risk factor for hypertension but is not a risk factor for diabetes in elderly population." (PMID 24354906, 2013). "Twelve women were treated for hypertension, nine of whom needed two or more antihypertensives, including methyldopa (n = 5), ACE-Inhibitors or AT II receptor inhibitors (n = 7), ß-blockers (n = 7), diuretics (n = 8), monoxidine (n = 2), dihydralazine (n = 1), and clonidine (n = 1)." (PMID 23840514, 2013). "Therefore, following up on our previous genomewide scan study we set out to map QTLs for serum ACE activity and to examine their effects on hypertension by analysis of variance approach and measured haplotype analysis." (PMID 23469169, 2013). "Overactivation of brain ACE-Ang II-AT1R axis was found to take part in the development and maintenance of hypertension, an important risk factor for ischemic stroke, by elevating oxidative stress in brain and increasing the activity of sympathetic nervous system." (PMID 23997755, 2013). "The univariate regression analysis of our study revealed that types of cooking oil, BMI, WC, preference for salty foods, family history of hypertension, family history of diabetes mellitus, TG, CHOL, FBG, relative ACE mRNA, and ACE activity revealed associations with hypertension." (PMID 24098401, 2013). "In addition, our data also indicate that plasma ACE activity (adjusted OR was 1.13(95% CI: 1.08-1.18)) was significantly related to hypertension." (PMID 24098401, 2013). "In one clinical trial an ACE inhibitor is used to treat hypertension." (PMID 24265719, 2013). "High ACE activity leads to increased concentration of angiotensin II and hypertension." (PMID 24359711, 2013). "ACE inhibitors are some of the most commonly prescribed medications for hypertension." (PMID 24053215, 2013). "A blend of Delonix regia carboxymethylated gum/sodium alginate is effective in encapsulating Phaseolus lunatus hydrolysate with ACE inhibitory activity, suggesting that it could be an effective delivery system in the preventative treatment of hypertension." (PMID 25937975, 2013).
Hypertension (continued). "In the present study, we genotyped nine ACE gene polymorphisms in a group of Mexican individuals with and without essential hypertension." (PMID 23741507, 2013). "The role of ACE gene in essential hypertension remained controversial." (PMID 24354906, 2013). "The present study was designed to explore the association of angiotensin converting enzyme (ACE) gene insertion/deletion (I/D, rs4646994) polymorphism, plasma ACE activity, and circulating ACE mRNA expression with essential hypertension (EH) in a Chinese population." (PMID 24098401, 2013). "Moreover, the ACE protein is a target for various pharmaceuticals (ACE inhibitors), especially in the treatment of hypertension." (PMID 23093944, 2012). "Considering the importance of diet in prevention of oxidative stress-related diseases including hypertension, this study was undertaken to evaluate the in vitro antioxidant and ACE inhibitory activities of selected culinary-medicinal mushrooms extracted by boiling in water for 30 min." (PMID 21716693, 2012). "Interventions to treat patients with diabetic nephropathy were generally considered of high clinical relevance, in particular the treatment of hypertension in patients with nephropathy (4.9), and, more specifically, use of ACE-inhibitors in diabetic nephropathy (4.5)." (PMID 22448219, 2012). "Prior work suggested that the ACE inhibitor would reverse vascular morphology changes associated with hypertension while the beta blocker would not, for example." (PMID 22518290, 2012). "There was no significance between any other analyzed risk factor and ACE I/D polymorphisms; even though DD genotype had been reported to be associated with hypertension and/or diabetes mellitus." (PMID 22333273, 2012). "Similarly, for the treatment of hypertension (6 interventions), one class was considered clinically particularly important, as well as in need of evidence (ACE inhibitors/AT1 antagonists: 4.4; 4.1)." (PMID 22448219, 2012). "Interestingly, supplementation of EZA modulated key enzyme related to hypertension such as ACE by 36% in serum of HFD animals and improve some of serum electrolytes such as Na+, K+, Cl−, Ca2+ and Mg2+." (PMID 23258993, 2012). "Moreover, maca significantly inhibited the hypertension relevant angiotensin I-converting enzyme (ACE) in vitro." (PMID 21977053, 2012). "Trial guidelines and bevacizumab prescribing information routinely recommend treating bevacizumab-induced hypertension with an ACE inhibitor or calcium channel blocker and continuing treatment rather than reducing the dose of the bevacizumab, so as not to deny patients potential benefit." (PMID 22531628, 2012). "Hypertension is present in approximately 16% of the adult population of the world, and 95% are categorized as essential hypertension treated with the major classes of antihypertensives including diuretics, ACE inhibitors, ARBs, β-blockers, and calcium channel blockers." (PMID 22792446, 2012). "Here, we analyzed the influence of pharmacological PKC inhibition on vascular function in a model that combines diabetes and hypertension, while angiotensin-converting enzyme (ACE) inhibitor Captopril (Capto) was used as a positive control in the blood pressure portion of the study." (PMID 21635764, 2011). "Therefore, ACE inhibitors having antioxidant properties are considered beneficial for the treatment of hypertension." (PMID 21810173, 2011). "Association between hypertension and ACE gene polymorphism had not been found in the general population, in some particular conditions, such as malignant hypertension, the D allele had been shown to be a significant risk factor." (PMID 21859496, 2011). "Interestingly, the formulation Om3/terp modulated key enzyme related to hypertension such as ACE by 37% in plasma and kidney." (PMID 22142357, 2011).